TLR4 (toll like receptor 4)
Diseases named in the same sentence as TLR4 in open-access papers (continued):
Sharing a sentence is not in itself a finding about the gene and the disease.
steatosis (continued). "The TLR4/MyD88 signaling pathway was demonstrated to be activated in the HBV-transgenic mice with NAFLD and HepG2.2.15 cells with SA-induced steatosis and contributed to inhibition of HBV replication." (PMID 36544761, 2022). "Furthermore, there was increased expression of FATP4 and TLR4 in adipose tissue and liver tissue in HFD-fed rats, which was associated with significant hypertrophy in the size of adipocytes and fatty degeneration of the liver hepatocytes, demonstrating steatosis." (PMID 36360622, 2022). "Moreover, the anti‐NAFLD effect of ezetimibe, as evidenced by the complete prevention and rescue of steatosis, together with the potential medicinal property of the TLR4 antagonist, could contribute to the development of new therapeutic strategies for this global health problem." (PMID 32123832, 2019). "Liver-specific TLR4-knockout (TLR4LKO) mice become obese when placed on a HF diet but remain insulin sensitive and are protected from the development of steatosis." (PMID 29666152, 2018). "By contrast in mice fed EtOH+Chol, ALT increased to ~270 U/L, steatosis was more extensive and mostly macrovesicular, and expression of proinflammatory molecules (HMGB-1, TLR4, TNFα, ICAM-1) and leukocyte infiltration increased substantially." (PMID 27676640, 2016). "In steatosis hepatic, HMGB-1, releasing from hepatocytes in response to FFAs, is promoting an increased TLR4 protein levels and release of hepatic pro-inflammatory and pro-fibrogenic cytokines." (PMID 24829591, 2014). "The interaction of LPS with Toll-like receptor 4 (TLR4) on Kupffer cells triggers the production of pro-inflammatory cytokines (TNF-α, IL-1β, IL-6), activating a sterile immune response that contributes to disease progression from steatosis to steatohepatitis." (PMID 40647333, 2025). "In summary, our study supports eNAMPT/TLR4 signaling as a clinically relevant, highly druggable therapeutic target with an eNAMPT-neutralizing biologic therapy identified as a potential strategy to retard the progression of NAFLD from steatosis to fibrosis." (PMID 36809677, 2023). "We observed that, compared with non-steatotic liver, the presence of steatosis resulted in reduced retinol-binding protein 4 and toll-like receptor 4 (TLR4) levels and increased peroxisome proliferator-activated receptor γ levels." (PMID 31547621, 2019). "In the HIV-Tg rats, binge alcohol increases LPS/endotoxin-mediated hepatic leptin and TLR4 level, which further activated Kupffer cells with up-regulated levels of MCP-1 and CCR2, at least partially, contributing to greater hepatic inflammation and steatosis." (PMID 26484872, 2015). "GLC could protect hepatocytes from oxidative stress and steatosis, and reduce extracellular HMGB1 levels, which blocks activation of macrophages via TLR4/NF-κB, and the expression of inflammatory cytokines was decreased to alleviate progression of steatohepatitis." (PMID 36278177, 2022). "Thus, the adaptor protein MyD88 is not essential for TLR4-mediated alcoholic liver injury and steatosis." (PMID 28852648, 2017). "Despite exhibiting improvement of steatosis, PNS produced no significant change in hepatic CD14 and TLR4 expression in ob/ob mice." (PMID 33656663, 2021).
cardiac hypertrophy (68 papers, 2011 to 2026). "Receptor-interacting serine/threonine-protein kinase 2 (RIP2) deficiency ameliorates cardiac hypertrophy through multiple signaling pathways that reduce TLR4/MyD88/NF-κB activation and MAPKs phosphorylation." (PMID 37113698, 2023). "Calcitriol infusion in the PVN ameliorates hypertensive responses and cardiac hypertrophy by decreasing TLR4-associated inflammation." (PMID 37113698, 2023). "While TLR4 deficiency protects mice from cardiac hypertrophy induced by a high-fat diet (HFD), it surprisingly leads to impaired cardiac function after chronic pressure overload due to aortic constriction (AAC)." (PMID 38140398, 2023). "NOD2 deficiency promoted cardiac hypertrophy and fibrosis by activating TLR4 and the MAPKs, NF-kB, and TGF-β/Smad pathways." (PMID 35990977, 2022). "The TLR4 pathway has been associated with HF and is involved in adverse cardiac remodeling and hypertrophy." (PMID 34769252, 2021). "Taken together, the results indicate that DSELD alleviates myocardial hypertrophy by inhibiting the expressions of TLR4 signaling pathway-associated proteins." (PMID 35046797, 2021). "In aged mice, cardiac hypertrophy was evidenced by an increased ratio of heart weight/tibial length, and loss of TLR4 significantly prevented cardiac hypertrophy in aged mice." (PMID 34740366, 2021). "We and others previously showed that TLR4 deficiency in mice results in a lower degree of cardiac hypertrophy after MI or pressure overload induced by transverse aortic constriction (TAC)." (PMID 34769252, 2021). "In general, high TLR4 levels are associated with cardiac hypertrophy and are increased in the myocardium of patients with advanced HF." (PMID 34769252, 2021). "Loss of TLR4 prevented cardiac hypertrophy and improved cardiac function and endothelium-dependent vascular relaxation in aged mice." (PMID 34740366, 2021). "It has been elucidated that TLR4 is associated with inflammatory response, and downregulation of TLR4 expression attenuates cardiac hypertrophy and prevents inflammation." (PMID 33324685, 2020). "Specifically, they applied AB in TLR4 deficient and wild type mice, and found that knocking out TLR4 reduces cell size and improves cardiac hypertrophy." (PMID 33324685, 2020). "More recently, it was shown that erythropoietin exerts a protective role in myocardial fibrosis and cardiac hypertrophy, and the mechanism is associated with downregulating TLR4 expression by activating the PI3K/Akt signaling pathway." (PMID 33324685, 2020). "Given TLR4's significance, it is imperative to review the molecular mechanisms and roles underlying TLR4 signaling in cardiac hypertrophy." (PMID 33324685, 2020). "Activation of toll-like receptor 4 (TLR4), an important regulator of inflammation, causes the progression of cardiac hypertrophy and injury." (PMID 33159115, 2020). "Previously, it was reported that inhibition of mTOR by rapamycin attenuates pathological hypertrophic response by downregulating NF-κB signaling, whereas rapamycin has an additional improvement for cardiac hypertrophy in TLR4 deficient mice." (PMID 33324685, 2020). "This view is supported by the finding that cardiac hypertrophy is prevented in TLR4-deficient mice, and that TLRs are crucial inducers of cardiac hypertrophy and cardiomyocyte apoptosis." (PMID 26448184, 2015). "Chronic hypertension causes cardiac hypertrophy, characterized by low-grade inflammation and accompanied by increased expression and activity of TLR4, and elevated gene expression of TNF-α and IL-6 in cardiac tissue." (PMID 24223475, 2013). "Functional TLR4 deficiency has been shown to significantly attenuate cardiac hypertrophy." (PMID 35860690, 2022). "Furthermore, TLR4 mediates Ang II-induced cardiac hypertrophy and is associated with myocardial TNF-α and IL-1β levels and NF-κB activity." (PMID 36247184, 2022).
cardiac hypertrophy (continued). "Additionally, increased TLR4 expression has been associated with mitochondrial dysfunction in an isoproterenol-induced cardiac hypertrophy rat model as treatment with a TLR4-agonist, LPS, induced oxidative stress accelerating cardiac disease." (PMID 36012897, 2022). "Cardiac hypertrophy is closely associated with the TLR4/MyD88/NF-κB signaling pathway." (PMID 33324685, 2020). "The possible mechanisms by which MD-1 regulates cardiac hypertrophy may be associated with its downstream targets in the TLR4 signalling pathway." (PMID 28165494, 2017). "However, loss of TLR4 prevented aging-induced cardiac hypertrophy." (PMID 34740366, 2021). "Conversely, UBE3A knockdown by siRNAs exacerbated isoproterenol-induced cardiac hypertrophy by activating the TLR4/MMP-9 pathway." (PMID 38515760, 2024). "Meanwhile, the NF-κB pathway and the JAK/STAT3 pathway, in which Toll-like receptor 4 is involved, are thought to be involved in cardiac hypertrophy." (PMID 38402404, 2024). "Nucleotide-binding oligomerization domain-2 (NOD2)-knockdown in mice increases cardiac hypertrophy and fibrosis by upregulating multiple pathways, including the TLR4/NF-κB, TLR4/MAPK, and TGF-β/Smad pathways." (PMID 37113698, 2023). "Apart from these, renal denervation and repetitive hyperthermia (RHT) attenuate the development of cardiac hypertrophy, at least in part by inhibiting TLR4 expression." (PMID 37113698, 2023). "Mice treated with a TLR4 inhibitor showed a significant decrease in all these parameters, which shows the involvement of TLR4 receptor signaling in cardiac hypertrophy." (PMID 37239362, 2023). "Activation of TLR4 in cardiac cells has been shown to initiate the release of inflammatory cytokines, contributing to cardiac hypertrophy." (PMID 38140398, 2023). "An isoproterenol-induced cardiac hypertrophy model of male SD rats showed a significant increase in TLR4 expression along with mitochondrial dysfunction." (PMID 37239362, 2023). "On the other hand, TLR4 activation also has a positive role in inducing cardiac hypertrophy when needed." (PMID 38140398, 2023). "The complexity of TLR4 signaling, along with interactions with other pathways, underscores the challenges in translating these findings into therapeutic strategies for cardiac hypertrophy and fibrosis." (PMID 38140398, 2023). "We found that TLR4−/− mice were protected from cardiac hypertrophy when exposed to HFD in comparison to their WT counterparts." (PMID 38140398, 2023). "It has also been reported that TLR4 plays an important role in the regulation of cardiac hypertrophy, and that TLR4 participates in cardiac hypertrophy regulation through the mTOR signaling pathway." (PMID 35855640, 2023). "In response to stress or injury, TLR4 can initiate an adaptive response, leading to cardiac hypertrophy." (PMID 38140398, 2023). "A significant link between inflammation, oxidative stress and cardiac hypertrophy constitutes toll-like receptor 4 (TLR4) signaling." (PMID 36012897, 2022). "TLR4 is known as a co-player in cardiac remodeling after myocardial infection and cardiac hypertrophy." (PMID 36289897, 2022). "Nevertheless, a recent report suggests that inflammation, specifically the role of TLR4 signaling, plays an important role in the pathological mechanisms of cardiac hypertrophy." (PMID 35130326, 2022). "The present study indicated that TIPE2 represses macrophage activation by targeting TLR4, subsequently inhibiting cardiac hypertrophy." (PMID 35528518, 2022). "Antibiotics reduced the HW/BW ratio, cardiac hypertrophy/fibrosis, and the level of TLR4 and IL-1β in the ileum, and rescued the muscularis layer thickening, villus length, and numbers of Paneth and goblet cells in the ileum of HSD-ANP−/− mice." (PMID 35956306, 2022). "Similar to the effect of TIPE2 overexpression, treatment with a TLR4 inhibitor mitigated the adverse cardiac hypertrophy." (PMID 35528518, 2022).
cardiac hypertrophy (continued). "In summary, TIPE2 protects against adverse cardiac hypertrophy by targeting TLR4 in the membrane of macrophages in the heart and subsequently attenuating prohypertrophic Akt signaling in cardiomyocytes." (PMID 35528518, 2022). "Meanwhile, BRD4 silencing protects against Ang II-induced cardiac hypertrophy via the upregulation of Nrf2-HO-1 and downregulation of TLR4-NF-κB signaling pathways." (PMID 36247184, 2022). "The cardioprotective effects of BRD4 silencing, including cardiac hypertrophy, oxidative stress, and inflammatory cytokine production, were all significantly attenuated by TLR4 overexpression." (PMID 36247184, 2022). "Current elucidation indicates that the development of myocardial hypertrophy is related to the TLR4 signaling pathway." (PMID 35046797, 2021). "The mechanism by which TLR4 influences myocardial hypertrophy mainly involves the MyD88-dependent pathway and MMP9-dependent pathway." (PMID 35046797, 2021). "The results demonstrate that DSELD ameliorates myocardial hypertrophy via inhibiting the TLR4-mediated myocardial inflammation." (PMID 35046797, 2021). "Numerous groups have studied the role of TLR4/MAPK signaling in cardiac hypertrophy using pharmacological inhibitors or genetic knockout mice, that directly or indirectly regulate ERK1/2, JNK, and p38 MAPK." (PMID 33324685, 2020). "Angiotensin II infusion induced cardiomyopathy in db/db mice, manifested by cardiac hypertrophy, myocardial fibrosis and inflammation (TNFα, TLR4)." (PMID 31924211, 2020). "This section mainly describes the elaborate network of TLR4-related signaling pathways during cardiac hypertrophy." (PMID 33324685, 2020). "In this review, we discuss TLR4-related inflammatory signaling and their intricate molecular mechanism in cardiac hypertrophy, such as ligands, co-receptors, inflammatory pathways, immune cells, and inflammatory mediators." (PMID 33324685, 2020). "During progression of cardiac hypertrophy, TLR4 ligands play crucial roles in modulating inflammatory response by binding to TLR4." (PMID 33324685, 2020). "Recently, several laboratory found that CaMK II as a downstream effector of TLR4 signaling plays a key role in pathogenesis of cardiac hypertrophy under hyperlipidemia conditions." (PMID 33324685, 2020). "Another possible mechanism of cardiac hypertrophy is that TLR4 plays a role via the regulation of CaMK II, indicating that TLR4 downstream networks are more complicated than previously assumed and involve inflammasome activation or CaMK II participation." (PMID 33324685, 2020). "It has been reported that blocking MyD88, the downstream adapter protein for TLR4 signaling, significantly improves mortality and reduces oxidation-CaMK II expression and cardiac hypertrophy." (PMID 33324685, 2020). "Regardless of its blockage or activation, these studies strongly suggest that TLR4 is critical in the regulation of cardiac hypertrophy." (PMID 33324685, 2020). "In particular, MIAT knockdown can enhance miR-93 and inactivate the PI3K/Akt/mTOR pathway via regulating the TLR4 in angiotensin II-induced cardiac hypertrophy." (PMID 32605220, 2020). "Cardiac hypertrophy is accompanied by activation of TLR4-mediated inflammatory pathways, which subsequently induce production of hypertrophic markers, chemokines, adhesion molecules, and a large number of pro-inflammatory cytokines." (PMID 33324685, 2020). "Conversely, central blockade of TLR4 reportedly reduced mean arterial blood pressure, suppressed production of pro-inflammatory mediators, and eventually attenuated cardiac hypertrophy." (PMID 33324685, 2020). "Collectively, these data suggest that TLR4-mediated MAPKs activation plays an important role in cardiac hypertrophy." (PMID 33324685, 2020). "Meanwhile, accumulating evidence suggests that TLR4 is an essential player in the progression of cardiac hypertrophy." (PMID 33324685, 2020).
cardiac hypertrophy (continued). "Recently, blockade of TLR4 was found to display less hypertrophy in isoproterenol (ISO)-induced cardiac hypertrophy in rats." (PMID 33324685, 2020). "In response to AngII, MIAT acts as a molecular sponge of miR-93 which participates in the inactivation of the PI3K/Akt/mTOR pathway via targeting TLR4 in AngII-induced cardiac hypertrophy." (PMID 32754048, 2020). "Recent studies in the rat models of ischemic brain injury or angiotensin II-induced cardiac hypertrophy show that this effect of PTX is due to the inhibition of toll-like receptor 4/NFκB pathway activity." (PMID 29324683, 2018). "We found increased cardiac TLR4 expression along with increased oxidative stress and mitochondrial dysfunction in hypertrophy heart." (PMID 28690610, 2017). "Overall, these results indicate that PRDX2 promotes angiogenesis and myocardial hypertrophy but this is mediated by TLR4." (PMID 28765537, 2017). "Further studies are required to connect the missing link between the role of TLR4 in mitochondrial dysfunction and cardiac hypertrophy." (PMID 28690610, 2017). "Toll-like receptor 4 mRNA and protein expression was significantly (p < 0.05) increased in rat hypertrophy heart as compared to control." (PMID 28690610, 2017). "Our data showed that inhibition of TLR4 in hypertrophy group attenuated cardiac hypertrophy through restoring cardiac redox balance and mitochondrial dysfunction." (PMID 28690610, 2017). "To confirm the role of TLR4 on mitochondrial function in cardiac hypertrophy, we have analyzed the protein expression of ETC complexes in heart of these animals." (PMID 28690610, 2017). "Our results suggest that TLR4 mediates prenatal LPS-induced pulmonary hypertension and cardiac hypertrophy." (PMID 29137270, 2017). "The study proposes a strong rationale to investigate the potential application of TLR4 inhibitor and agonist in the treatment of cardiac hypertrophy and mitochondrial dysfunction." (PMID 28690610, 2017). "Previous studies support that activation of TLR4 contributes to cardiac hypertrophy, while genetic or pharmacological inhibition of TLR4 attenuates myocardial hypertrophy." (PMID 27355349, 2016). "VIPER treatment in SHR rats caused a significant decrease in the HW/BW ratio as well as ANP levels in comparison with SHR + CP, suggestive of reduced cardiac hypertrophy by blockade of TLR4 within the PVN of SHR." (PMID 25879545, 2015). "More importantly, TLR4 blockade within the PVN resulted in a significant reduction in ANP and the HW:BW ratio in hypertensive rats, suggesting reduced cardiac hypertrophy by TLR4 blockade." (PMID 25879545, 2015). "TLR4-mediated recognition of host-derived molecules such as fibrinogen activates the immune system and sustained TLR4 activation induces cardiac hypertrophy." (PMID 26588247, 2015). "TLR4/MYD88 has been shown to have a critical role in NF-κb-mediated cardiac hypertrophy and inflammation." (PMID 25546437, 2014). "For instance, the lncRNA MIAT promotes cardiac hypertrophy by regulating miR-93/Tlr4." (PMID 40874024, 2025). "This suggests that modulating the TLR4 signaling pathway could be an effective strategy for managing the pathophysiology of cardiac hypertrophy." (PMID 41357167, 2025). "UBE3A is vital for alleviating cardiac hypertrophy via the UBE3A/TLR4/MMP-9 pathway." (PMID 38515760, 2024). "In addition to the TLR4 pathway, the PI3K/Akt/mTOR signaling pathway has also been shown to play a role in cardiac hypertrophy caused by pressure overload and blocking it almost diminished hypertrophy." (PMID 38140398, 2023). "The activation of TLR4 signaling in cardiac cells triggers intracellular signaling pathways, immune cell infiltration, and the secretion of inflammatory mediators, which contribute to cardiac hypertrophy." (PMID 38140398, 2023).